INS (insulin)
Diseases named in the same sentence as INS in open-access papers (continued):
Sharing a sentence is not in itself a finding about the gene and the disease.
acute coronary syndrome (38 papers, 2005 to 2025). Signs and symptoms related to acute ischemia of the myocardium secondary to coronary artery disease. "Epidemiological findings show that increased levels of ceramides found in acute coronary syndrome (ACS) patients have been linked to insulin sensitivity and are associated with a vulnerable plaque phenotype during intravascular ultrasound." (PMID 41190023, 2025). "We performed a study to evaluate the effect of intensive insulin therapy in association with GIK on 1‐year outcome in patients hospitalized for acute coronary syndrome." (PMID 29138181, 2017). "The AR index, combined with adiponectin and resistin levels, is a cost-effective and a precise diagnostic biomarker for insulin sensitivity and is a predictor of acute coronary syndrome." (PMID 26930652, 2016). "During the study period, one patient in the “insulin use” and two patients in the “non-insulin use” group developed acute coronary syndrome (p = NS)." (PMID 36559020, 2022). "This study plans to enroll 5400 patients (HbA1c 6.5%-11.0% on monotherapy or combination antidiabetic therapy, or 7.0%-9.0% if the regimen includes insulin) who have a diagnosis of acute coronary syndrome within 15 to 90 days before randomization." (PMID 22248301, 2012). "Several studies have evaluated glucose-related therapies as strategies to improve outcome in acute coronary syndromes, such as high dose glucose-insulin-potassium (GIK) infusion, or combined glucose-insulin infusion to reduce glucose levels." (PMID 16359559, 2005). "Specifically, Cer(d18:1/18:0) and its ratio to Cer(d18:1/24:0) have recently been found able to accurately predict acute coronary syndrome-T2D, confirming the previous evidence which suggests that Cer(d18:1/18:0) is particularly adverse for insulin sensitivity and promotes adipose inflammation." (PMID 36677773, 2023). "Variants in LCA5 gene were shown to modify glucose response in a clinical trial of insulin and potassium (GIK) infusion in acute coronary syndromes." (PMID 33472578, 2021). "Glucose is an important preferential substrate for energy metabolism during acute coronary syndrome (ACS) attack, although insulin resistance (IR) increases during ACS." (PMID 31127136, 2019). "The aim of this review is to analyse the molecular mechanisms by which SIH may favour a worse prognosis in non-diabetic patients with acute coronary syndrome and identify new therapeutic strategies, in addition to insulin therapy, for a more appropriate treatment and improved outcomes." (PMID 33466656, 2021). "Among acute coronary syndrome patients undergoing PCI and receiving maintenance therapy with prasugrel, insulin-treated diabetic patients have higher PR than patients without DM or non insulin-treated diabetic patients." (PMID 26025572, 2015). "Research may be also focused on determining how the severity levels of CAD (stable CAD or acute coronary syndrome), CKD (patients on dialysis or not), and DM (treated with oral antidiabetics or insulin-requiring) may influence mortality in each of the subgroups of patients with HF and AF." (PMID 34356208, 2021).
Arthritis (38 papers, 2008 to 2026). Inflammation of a joint. "The observed association suggests potential underlying mechanisms that link insulin resistance, metabolic dysfunction, and chronic inflammation to the pathogenesis of arthritis." (PMID 37608322, 2023). "Enhancing the management of glucose, lipids, and insulin sensitivity may significantly reduce the risk of arthritis." (PMID 40672425, 2025). "In this review, we focalize on the bidirectional cause-effect relationship between impaired insulin signaling and arthritis analyzing how insulin signaling may be involved in the aberrant immune response implicated in arthritis and how inflammatory mediators affect insulin signaling." (PMID 33995414, 2021). "Serum levels of cortisol, growth hormone (GH) and thyroid-stimulating hormone (TSH) were higher in animals with arthritis (AG), whereas serum levels of insulin, triiodothyronine (T3) and thyroxine (T4) were lower." (PMID 40005882, 2025). "Leptin and adiponectin, being important adipokines, not only regulate insulin sensitivity and lipid metabolism but also contribute to the occurrence of arthritis by modulating inflammatory and immune responses." (PMID 38481325, 2024). "In arthritis, abnormalities of glucose homeostasis were described in 1920; and in 1950 combined glucose and insulin tests unmistakably demonstrated IR." (PMID 25608958, 2014). "Adiponectin is an adipokine that regulates energy metabolism and insulin sensitivity, but recent studies have pointed also to a role in inflammation and arthritis." (PMID 22077999, 2011). "The present work confirms that an oral intake of the antidiabetics rosiglitazone or pioglitazone can reduce the severity of arthritis but indicates that the doses required for an anti-arthritic effect exceed those sufficient to restore insulin sensitization." (PMID 18199331, 2008). "As a result, studies related to insulin and arthritis have gained importance in recent years." (PMID 37608322, 2023). "In summary, through its integrated signaling network, insulin regulates intracellular and intercellular pathways in immune cells, in cartilage and in synovial tissue, behaving as a crucial modulator of the inflammatory response observed in arthritis." (PMID 33995414, 2021). "The decrease in this cytokine observed in our model may be due to the acute inflammation induced by the arthritis, yielding the insulin insensitivity." (PMID 26742100, 2016). "Finally, daily doses of thiazolidinediones (TZDs) as high as 100 mg/kg/day were reported to be effective in experimental arthritis although these doses are far above those required to restore insulin sensitivity." (PMID 18199331, 2008). "In conclusion, our study shows that blood levels of insulin combined with age, RA classification score, and IFNg were predictive of MTX response in early treatment-naïve arthritis patients." (PMID 40643485, 2025). "Food restriction during arthritis led to a reduction of basal glucose, and insulin plasma levels, and consequently to a reduction of HOMA index compared to food restriction in controls or to the other dietary regimes during arthritis." (PMID 20953376, 2010). "Similar to insulin, IGF-1R signaling plays a role in inflammation mediated by T cells in arthritis." (PMID 33995414, 2021). "However, plasma insulin levels were significantly increased in lean CIA, OB, and OB CIA mice, which was translated into an increase in HOMA-IR in these three groups of mice, suggesting that IR in arthritis is due to the high levels of insulin." (PMID 34721412, 2021). "According to the HOMA-IR data, prednisolone treatment significantly reduced insulin sensitivity in a dose-dependent manner in both non-arthritic (p = 0.028) and arthritic mice (p = 0.0001 after correction for differences in arthritis scores between the groups)." (PMID 25181348, 2014). "Arthritis decreased serum leptin, adiponectin, and insulin (P<0.01) but not resistin levels." (PMID 23781298, 2012).
Arthritis (continued). "Now imagine that this same patient lives alone, has minimal family support, and has severe crippling arthritis such that she could not inject insulin even if she were motivated to do so." (PMID 19516910, 2009).
dilated cardiomyopathy (38 papers, 2011 to 2025). Cardiomyopathy which is characterized by dilation and contractile dysfunction of the left and right ventricles. "IGFBP2 plays an important role in the IGF growth axis, with elevated levels associated with lower fasting insulin and fasting glucose, but with greater mortality in older adults and in patients with dilated cardiomyopathy." (PMID 33019943, 2020). "GLP-1 infusion and the associated improvement in myocardial insulin action, mitochondrial protein expression and coronary flow reserve was associated with a prolonged course of dilated cardiomyopathy and increased survival in Old + GLP-1 compared to Old-Control." (PMID 25078106, 2014). "The analysis uncovered significant enrichment in pathways related to adrenergic signaling, dilated cardiomyopathy, myocardial contractility, cAMP signaling, and insulin secretion." (PMID 40076920, 2025). "Across all three comparisons, the shared pathways were associated with muscle disease (Hypertrophic cardiomyopathy and Dilated cardiomyopathy) and metabolic disorder (Insulin secretion)." (PMID 38786923, 2024). "The up-regulated genes were annotated to multiple endocrine and metabolic-related pathways, including “endocrine resistance,” “cortisol synthesis, and secretion,” “dilated cardiomyopathy,” and “insulin secretion”." (PMID 35606885, 2022). "Consistent with that finding, there is growing evidence about myocardial insulin insensitivity in dilated cardiomyopathy (DCM)." (PMID 31935874, 2020). "KEGG pathway analysis showed that genes involved in insulin secretion, dilated cardiomyopathy, arrhythmogenic right ventricular cardiomyopathy (ARVC), cell adhesion molecules and hypertrophic cardiomyopathy (HCM) were downregulated in MEC compared to ESC." (PMID 30082875, 2018). "In conscious dogs with pacing-induced dilated cardiomyopathy, 7-36a administration significantly increased both basal and insulin-stimulated myocardial glucose uptake, and markedly improved hemodynamics in the absence of increases in plasma insulin." (PMID 28194113, 2017). "Blood levels of creatine have been negatively associated with insulin sensitivity, lower in liver steatotic versus NASH patients, and elevated in dilated cardiomyopathy." (PMID 27355821, 2016). "However, he had high HOMA-IR, low adiponectin levels, required insulin early in his disease natural history and suffered from dilated cardiomyopathy." (PMID 27120622, 2016). "Thus, while exenatide can normalize whole-body insulin sensitivity and myocardial glucose uptake in mice that have advanced dilated cardiomyopathy, cardiac contractile function and survival are improved but not to perfect health." (PMID 21359201, 2011). "The proteins involved in the TGF-beta signaling pathway, mTOR signaling pathway, Rap1 signaling pathway, carbon metabolism, calcium signaling pathway, insulin signaling pathway, and dilated cardiomyopathy pathway may be related to the muscle growth and development of Jersey-yak." (PMID 38338049, 2024). "Namely, DEL are involved in the regulation of dilated cardiomyopathy (DCM), hypertrophic cardiomyopathy (HCM), insulin signaling pathway, and mTOR signaling pathway." (PMID 34880964, 2021). "We previously demonstrated that older beagles have impaired whole body and myocardial insulin responsiveness (MIR), and that glucagon-like peptide-1 (GLP-1 amide) improves MIR in young beagles with dilated cardiomyopathy (DCM)." (PMID 25078106, 2014). "Additionally, enriched DEGs reported in the 39 °C vs. 37 °C comparison showed a linkage to KEGGs pathways such as hypertrophic cardiomyopathy, insulin signaling pathway, AMPK signaling pathway, dilated cardiomyopathy, and lysosome." (PMID 37686405, 2023).
dilated cardiomyopathy (continued). "In addition, the insulin signaling pathway, hypertrophic cardiomyopathy (HCM), glycolysis/gluconeogenesis, and dilated cardiomyopathy can be involved in hypoxic adaptation." (PMID 28623314, 2017).
gallstones (38 papers, 2008 to 2025). Solid crystalline precipitates in the biliary tract, usually formed in the gallbladder, resulting in the condition of cholelithiasis. "These hormonal changes affect satiety, insulin secretion, and gut motility, exacerbating the metabolic disturbances associated with gallstone formation." (PMID 40370800, 2025). "CTI is a rapid, accessible, and cost-effective biochemical test that provides information on inflammation and insulin resistance status, as well as their reciprocal and synergistic associations with gallstones." (PMID 40988273, 2025). "One animal study of mice with increased plasma insulin secretion due to hepatic IR has demonstrated that insulin itself will predispose to cholesterol gallstone formation due to an increase in the secretion of biliary cholesterol and lithogenic bile salt." (PMID 30555418, 2018). "Furthermore, visceral fat is closely linked to insulin resistance, which impairs gallbladder motility and bile emptying, thereby further facilitating gallstone formation." (PMID 40370800, 2025). "High levels of insulin in obese individuals can lead to increased cholesterol production by stimulating 3-hydroxy-3-methylglutaryl-coenzyme a reductase activity, which consequently raises gallstones risk." (PMID 39758317, 2024). "Furthermore, the triglyceride glucose-waist height ratio (TyG-WHtR) was superior to triglyceride glucose-body index mass (TyG-BMI) and triglyceride glucose-waist circumference (TyG-WC) in identifying gallstone risk in a new indicator for assessing insulin resistance." (PMID 40748974, 2025). "In addition, GDF-15 may be a proxy for immobilization, impaired fasting glucose, and insulin resistance, which are risk factors for the development of gallstones." (PMID 35769993, 2022). "Sleep disorders reduce insulin sensitivity, perturbing bile composition and promoting cholesterol supersaturation in bile, which are key steps in gallstone pathogenesis." (PMID 40313242, 2025). "The dietary fiber in taro can combine with cholesterol to promote the circulation of bile in the body and effectively prevent gallstones; resistant starch controls insulin secretion, reduces cholesterol synthesis and prevent gallstones." (PMID 40995184, 2025). "Future comprehensive research and interventions focusing on reducing phthalate metabolite exposure and managing insulin levels are expected to be pivotal in addressing and lowering the prevalence of gallstones." (PMID 38903577, 2024). "Resistant starch can reduce the incidence of gallstones through the regulation of insulin secretion." (PMID 37238887, 2023). "Positive correlations between serum leptin and BMI, CCK, total cholesterol, and insulin were found in the gallstone group." (PMID 33375615, 2020). "Insulin treatment has been shown to increase the biliary saturation index, resulting in cholesterol precipitation and gallstone formation." (PMID 29390977, 2018). "Insulin affects cholesterol saturation and gallbladder motility, an important factor in the formation of gallstones." (PMID 29088261, 2017). "A diet rich in refined sugar increase insulin, hepatic cholesterol synthesis, and bile cholesterol saturation and impair gallbladder motility, resulting in an increase of gallstone formation." (PMID 29169372, 2017). "Elevated BMI remains associated with an enlarged CBD, influenced by factors such as biliary stasis, gallstone development, insulin resistance, changes in lipid metabolism, and pressure from abdominal fat, leading to heightened cholesterol levels and gallstone formation." (PMID 41141869, 2025). "This association remained robust after adjusting for confounders, suggesting that such diets may promote gallstone formation through exacerbation of insulin resistance." (PMID 41368311, 2025).
gallstones (continued). "It has now been shown that IR can cause gallbladder stones to develop or become exacerbated in many studies, and visceral obesity and hepatic insulin resistance may be central to promoting cholesterol bile supersaturation and gallstone formation." (PMID 36263324, 2022). "Furthermore, mediation analyses indicated that phthalate metabolites may play a role in the development of gallstones by influencing insulin secretion." (PMID 38903577, 2024). "According to one study, pioglitazone is an antidiabetic that prevents gallstone formation, liver damage, and gallbladder damage, and guinea pigs treated with pioglitazone showed beneficial changes in the biliary cholesterol and bile acids, blood glucose, insulin, and lipid distribution." (PMID 36263324, 2022). "Compared to those without gallstones, individuals with gallstones had higher BMI, HOMA-IR, HOMA-β, fasting insulin, MECPP, MEOHP, MCOP, and ΣDEHP levels, alongside lower HOMA-IS and MCPP concentrations." (PMID 38903577, 2024).